CPS1 (carbamoyl-phosphate synthase 1)
Diseases named in the same sentence as CPS1 in open-access papers (continued):
Sharing a sentence is not in itself a finding about the gene and the disease.
epilepsy (1 paper, 2017). A brain disorder characterized by episodes of abnormally increased neuronal discharge resulting in transient episodes of sensory or motor neurological dysfunction, or psychic dysfunction. "For patients with a previous history of epilepsy, the administration of levocarnitine may be worth trying, because it may activate β-oxidation and the activity of CPS1, thereby activating the urea cycle and reducing the blood concentration of ammonia." (PMID 28690671, 2017).
esophagus carcinoma (1 paper, 2023). "NAGS and CPS1 genes were markedly overexpressed in esophageal carcinoma and kidney chromophobe samples, respectively." (PMID 37047726, 2023).
fibrolamellar carcinomas (1 paper, 2021). "Furthermore, HCC of macrotrabecular-massive, scirrhous, and lymphocyte-rich subtypes, as well as fibrolamellar carcinomas and mixed HCC-CCC tumors had generally lower CPS1 expression." (PMID 33670206, 2021).
heart defects (1 paper, 2020). "Additionally, we found three variants in CPS1, one in a homozygous state, a gene for which neonatal susceptibility to PAH has been suggested with an increase of pulmonary arterial pressure after a surgical repair of congenital heart defects." (PMID 33007923, 2020).
hepatitis C infection (1 paper, 2021). "However, CPS1 has also been demonstrated to be released from non-neoplastic hepatocytes upon liver damage and upon hepatitis C infection, and may therefore lack the necessary specificity for a neoplastic origin, for example when measured in blood." (PMID 33670206, 2021).
Hypercholesterolemia (1 paper, 2023). An increased concentration of cholesterol in the blood. "A decrease expression of CPS-1 relates to a reduction of ammonia detoxification in various defects especially in hypercholesterolemia and fatty liver (reviewed in Ref." (PMID 38027599, 2023).
Hyperglycemia (1 paper, 2024). An increased concentration of glucose in the blood. "In the glucagon tolerance test, we observed that the hepatic knockdown of CPS1 notably reduced fasting blood glucose levels and subsequently weaked the glucagon-induced hyperglycemia in mice." (PMID 39193349, 2024). "Our findings revealed that CPS1, a rate-limiting enzyme in the urea cycle, significantly exacerbates glucagon-induced hyperglycemia." (PMID 39193349, 2024). "The specific role of carbamoyl phosphate synthetase 1 (CPS1), a rate-limiting enzyme in the urea cycle, in the development versus the persistence of glucagon-induced hyperglycemia has not been previously established." (PMID 39193349, 2024).
hyperinsulinism (1 paper, 2012). Abnormally high levels of insulin in the blood. "Furthermore, abnormally low liver CPS1 activity has been reported in patients with genetically demonstrated NAGSD and in the hyperinsulinism-hyperammonemia syndrome (a defect involving glutamate dehydrogenase)." (PMID 22642880, 2012).
influenza infection (1 paper, 2014). "A previous study examining the effect of influenza infection on CPS1 and OTC activities in WT B6 mice showed appreciable reductions in CPS1 (12%) and OTC (17%) enzyme activities." (PMID 24271778, 2014).
lactic acidosis (1 paper, 2025). Metabolic acidosis characterized by the accumulation of lactate in the body. "For instance, CPS1 or NAGS deficiency typically lacks the pronounced lactic acidosis and ketosis observed in CA-VA deficiency." (PMID 40862046, 2025).
learning disabilities (1 paper, 2021). "Individuals with a CPS1 deficiency can present with a wide range of clinical manifestations, including headache, behavioral or psychiatric problems, learning disabilities, sleep disorder, periodic vomiting, seizures, coma, and even death." (PMID 34294844, 2021).
lentivirus infection (1 paper, 2024). Virus diseases caused by the Lentivirus genus. "CPS1 was knocked down with lentivirus infection in PLC and Huh7 cells." (PMID 39387452, 2024).
liver cirrhosis (1 paper, 2019). "Therefore, heterozygosity for disease-causing CPS1 mutations is almost as prevalent as liver cirrhosis." (PMID 31366360, 2019). "Previous research has shown that there was an 80% reduction in GLUL activity and a 30% reduction in CPS1 activity in a rat model of liver cirrhosis." (PMID 31366360, 2019). "For example, liver cirrhosis results in decreased expression of GLUL and the urea cycle enzyme CPS1." (PMID 31366360, 2019). "We recognize that liver cirrhosis is a complex disease with many changes besides altered CPS1 and GLUL activity, so this model is a simplified representation of liver cirrhosis." (PMID 31366360, 2019).
liver failure (1 paper, 2013). A liver disease characterized by the liver losing or has lost all of its function. "Built on the previous reports, we hypothesized that in a Caucasian population of patients without liver failure and treated with VPA, genetically determined variations in CPS1 function would be associated with increased incidence of HA." (PMID 23997965, 2013).
lung squamous cell carcinoma (1 paper, 2025). "Three compounds (gallic acid, betulinic acid, and caffeic acid) had a significant inhibitory effect on lung squamous cell carcinoma via five biolabels (CPS1, CKM, CPT1B, COX5B, and COX4I1)." (PMID 41502520, 2025).
malaria (1 paper, 2021). Malaria is a serious and sometimes fatal disease caused by a parasite that commonly infects a certain type of mosquito which feeds on humans. "Targeting sporozoite PLS–hepatocyte CPS1 interaction should be explored as a novel malaria control strategy." (PMID 34799567, 2021).
metastatic disease (1 paper, 2026). "Despite these findings, the precise role of CPS1 in the metastatic process and whether its expression is altered in metastatic tumors remains an open question." (PMID 41356199, 2026). "This research not only elucidates how the aberrant expression of a metabolic enzyme can drive the crucial initial steps of tumor metastasis, but also establishes CPS1-mediated urea cycle reprogramming as a druggable metabolic vulnerability for combating metastatic disease." (PMID 41356199, 2026).
nasal polyps (1 paper, 2011). "Interestingly, numerous dilated blood vessels were observed in the AERD samples compared to the ATA samples, which provides indirect evidence of a possible role for CPS1 in the nasal polyps of AERD patients." (PMID 21829647, 2011).
nephritis (1 paper, 2016). Inflammation of renal tissue. "The top 5 up-regulated genes based upon fold change between groups were: carbamoyl-phosphate synthase 1 (CPS1), carboxypeptidase O (CPO), tubulointerstitial nephritis antigen (TINAG), solute carrier family 7, member 9 (SLC7A9), and solute carrier family 6, member 19 (SLC6A19)." (PMID 27093613, 2016).
Pan (1 paper, 2023). "Although some metabolic rate‐limiting enzymes (i.e. IDH1 and CPS1) demonstrated higher mutation rates in parts of cancer types, most metabolic rate‐limiting enzymes had lower mutation rates in Pan‐cancer human cancers." (PMID 36629054, 2023).
pancreatic cancer (1 paper, 2025). "Studies have shown that HCC and pancreatic cancer, among others, highly express CPS1, a urea cycle enzyme that promotes survival by enhancing ammonia detoxification." (PMID 41041303, 2025).
primary hyperoxaluria (1 paper, 2022). A hereditary disorder characterized by excessive oxalate production, leading to hyperoxaluria. "Ten samples were acquired from organ donors and six from patients receiving liver transplantation for inborn errors of intermediary metabolism (1 Primary Hyperoxaluria, 2 Maple Syrup Urine Disease), including UCDs (1 OTC and 2 CPS-1 deficiencies)." (PMID 36499207, 2022).
Rolandic epilepsy (1 paper, 2021). "Here, we present a child who had CBZ-induced aggravation of rolandic epilepsy and VPA-induced HA encephalopathy in the background of an unrecognised heterozygous gene variant of CPS1." (PMID 35003817, 2021).
sarcopenia (1 paper, 2025). Progressive decline in muscle mass due to aging which results in decreased functional capacity of muscles. "While AAV8.Null with AAV8.cre recombinase mice developed progressive weight loss and sarcopenia beginning at 14 days after administration of vectors (red squares), AAV8.CPS1 mice demonstrated stability of weight throughout the studies (blue triangles)." (PMID 40083646, 2025). "AAV8.CPS1-treated mice, however, were generally stable (blue triangles) (except in male mice around day 60 where 2 had elevated plasma ammonia and died shortly thereafter without evidence of weight loss or sarcopenia)." (PMID 40083646, 2025).
squamous carcinoma (1 paper, 2023). "We were very interested to find that DEX growth inhibition associated with LKB1 loss of function is not NSCLC histologic subtype specific and occurred in both adeno- and squamous carcinoma cell lines harboring high CPS1 expression." (PMID 37035141, 2023). "Growth inhibition by DEX was seen in almost all NSCLC subtypes that expressed CPS1, including adenocarcinomas (ADC), squamous cell carcinomas (SqCC)." (PMID 37035141, 2023).
urothelial carcinoma (1 paper, 2019). A malignant neoplasm derived from the transitional epithelium of the urinary tract (urinary bladder, ureter, urethra, or renal pelvis). "Carbamoyl phosphate synthase 1 expression in tissue was assessed in the 30 pairs of bladder tissue samples, and all samples were selected from urothelial carcinoma patients according to their pathological results." (PMID 31565867, 2019).
tumor (61 papers, 2011 to 2026). "In Kras or LKB1-mutated non–small cell lung carcinoma, up-regulation of CPS1 enhanced pyrimidine synthesis and promoted tumor growth." (PMID 41512056, 2026). "IDH1-mutant tumours resist ICIs via epigenetic–immune crosstalk, whereas CPS1-deficient tumours disrupt the urea cycle to alter the pH of the TME." (PMID 40861435, 2025). "Aberrant overexpression of the CPS1 is associated with the rapid proliferation of tumor cells, increasing the activity of pyrimidine biosynthesis through metabolic reprogramming." (PMID 39882072, 2024). "High tumor expression of carbamoyl phosphate synthase 1 (CPS1) was strongly linked to the presence of LKB1 mutations, was the best predictor of NSCLC dexamethasone (DEX) sensitivity (p < 10-16) but was not mechanistically involved in DEX sensitivity." (PMID 37035141, 2023). "We noticed that lower immunoreactivity of CPS1 in IHCC was associated with tumor progression (pT status) with statistical significance (p = 0.003)." (PMID 37443694, 2023). "The majority of CPS1 missense variants in gnomAD and tumor samples have REVEL scores that indicate an uncertain effect on CPS1 function." (PMID 37047726, 2023). "Similar fractions of CPS1 variants found in tumor samples and gnomAD were missense variants, while they represented the highest fraction of CPS1 variants found in patients with CPS1 deficiency." (PMID 37047726, 2023). "Lower immunoreactivity of CPS1 in IHCC was associated with tumor progression (pT status) with statistical significance (p = 0.003) in the current study." (PMID 37443694, 2023). "After the use of fatty acid inhibitor etomoxir (ETO), it can significantly inhibit the growth of CPS1 deficient tumor cells, and improve the sensitivity of tumor cells to sorafenib." (PMID 35655758, 2022). "CPS1 allows the mutated cancer cells to become resistant to arginine depletion, which is a major strategy of pro-tumor macrophages and tumor-associated myeloid cells to inhibit antigen-specific T cell responses." (PMID 36074553, 2022). "Combining Stony Brook taxanes with paclitaxel caused downregulation of CPS1 in the paclitaxel-resistant mouse xenograft tumor model in vivo." (PMID 35008510, 2021). "In particular, the combining of Stony Brook taxanes with paclitaxel caused downregulation of CPS1 in the paclitaxel-resistant mouse xenograft tumor model in vivo in comparison to paclitaxel alone." (PMID 35008510, 2021). "A previous study showed that CPS1 is the antigen for Hep Par 1, a commonly used antibody in diagnostic surgical pathology practice to determine the hepatocellular origin of neoplasms." (PMID 24763545, 2014). "Therefore, inhibiting CPS1 expression in tumor cells may cause excessive ammonia accumulation, but whether this accumulation can induce ammonia-induced cell death in tumor cells requires further validation through comprehensive experimental studies." (PMID 41041303, 2025). "Recent studies have highlighted a role of Carbamoyl Phosphate Synthetase 1 (CPS1), the urea cycle's rate-limiting enzyme, in tumor development." (PMID 41356199, 2026). "This compelling evidence strongly indicates that CPS1 inhibition significantly suppresses tumor metastasis." (PMID 41356199, 2026). "Metabolic plasticity is a key resistance mechanism, as evidenced by reports that CPS1 loss can induce sorafenib resistance and activate compensatory Fatty Acid β-Oxidation (FAO) to sustain tumor growth." (PMID 41356199, 2026). "Recent evidence suggests that CPS1, beyond its tumor-related roles, also influences metabolic diseases." (PMID 40438591, 2025). "Several small-molecule CPS1 inhibitors have been identified, showing potential in inhibiting CPS1 activity and inducing tumor cell death under experimental conditions." (PMID 41041303, 2025).
tumor (continued). "Compared with those of HH, the ARG1, CPS1, HNF4α, and HNF1α expression levels in tumor cell lines are minimal, if at all." (PMID 40963742, 2025). "Inhibition of glutamine metabolism or overexpression of CPS1 to reduce ammonia levels in T cells can significantly improve the survival of T cells in the tumor microenvironment and enhance their anti-tumor effect." (PMID 39596288, 2024). "Cluster 2 expressed zone 1 and 2 metabolic genes, including Cyp2f2, Pck1, Cps1, and Hamp analogous to the reprogrammed tumor cell population observed in the early-stage LNP-CTNNB1 treatment setting." (PMID 39711542, 2024). "Carbamoyl phosphate synthetase 1 (CPS1) is a tumor promoter that either supports pyrimidine synthesis or prevents the buildup of intratumoral ammonia." (PMID 38841188, 2024). "The overexpression of CPS1 promotes the proliferation of tumor cells by increasing the de novo biosynthesis of pyrimidine nucleotides, making CPS1 a novel target for anti-tumor drugs." (PMID 39882072, 2024). "HCC orthotopic transplantation tumor model revealed that knock‐down of CPS1 led to less number of tumor cells." (PMID 39387452, 2024). "These tumour cells were weakly positive for cytokeratin 7, thus imparting a biliary phenotype, while showing reduced expression of CPS1, a hepatocyte-specific marker." (PMID 37946160, 2023). "The connection between increased de novo biosynthesis of pyrimidine nucleotides, tumor cell proliferation, and aberrant CPS1 expression and activity made CPS1 an attractive target for antitumor drugs." (PMID 37047726, 2023). "Synonymous NAGS and CPS1 sequence variants were more frequent in tumor samples and gnomAD than in patients with NAGS or CPS1 deficiency, while citrin synonymous sequence variants were less frequent in gnomAD than in patients and tumor samples." (PMID 37047726, 2023). "NAGS, CPS1, and citrin sequence variants found in tumor samples were collected from the TCGA, COSMIC, and cBioPortal databases of tumor genomic information." (PMID 37047726, 2023). "Since CPS1 is a mitochondrial enzyme, CP produced by CPS1 in the mitochondria of tumor cells would have to be translocated into the cytoplasm to enter de novo pyrimidine biosynthesis." (PMID 37047726, 2023). "Another possibility is the activation of CPS1 in tumor cells by N-carbamylglutamate (NCG) produced by the human microbiota." (PMID 37047726, 2023). "This raises the question regarding the mechanism behind aberrant CPS1 activity that contributes to metabolic reprogramming towards increased de novo pyrimidine biosynthesis in tumor cells." (PMID 37047726, 2023). "Aberrant overexpression of carbamylphosphate synthetase 1 (CPS1) and SLC25A13 (citrin) genes has been associated with faster proliferation of tumor cells due to metabolic reprogramming that increases the activity of the CAD complex and pyrimidine biosynthesis." (PMID 37047726, 2023). "The study revealed that CPS1 knockdown can induce ammonia accumulation and inhibit the nucleic acid synthesis pathway resulting in the inhibition of tumor cells' growth." (PMID 36090899, 2022). "It was the first rate-limiting enzyme in urea cycle, involving tumor metabolism, while DNA methylation led to expression silencing of CPS1 in HCC." (PMID 33552157, 2021). "The xenograft model showed that decreased expression of CARD10 inhibited tumour growth and down‐regulated CPS1 expression in vivo." (PMID 31565867, 2019). "Notably, applying the CPS1 inhibitor to metastatic tumor cells in circulation, prior to colonization, effectively protected bones from metastatic damage." (PMID 41356199, 2026). "However, the effect of increased CPS1 activity on fumarate production and its role in tumor progression is not fully understood." (PMID 41356199, 2026).